TPP1 (tripeptidyl peptidase 1)
Diseases named in the same sentence as TPP1 in open-access papers (continued):
Sharing a sentence is not in itself a finding about the gene and the disease.
late infantile neuronal ceroid lipofuscinosis (23 papers, 2008 to 2025). A genetically heterogeneous group of neuronal ceroid lipofuscinoses (NCLs) typically characterized by onset during infancy or early childhood with decline of mental and motor capacities, epilepsy, and vision loss through retinal degeneration. "Late infantile NCL (LINCL) is caused by pathogenic variants in the CLN2 gene, which encodes the enzyme tripeptidyl peptidase 1 (TPP1)." (PMID 39940729, 2025). "Among NCL disorders, CLN2, also known as classical late infantile neuronal ceroid lipofuscinosis (cLINCL), is caused by mutations in the TPP1 gene which encodes the lysosomal protease Tripeptidyl peptidase 1 (TPP1)." (PMID 34749772, 2021). "For instance, the rare disease late infantile neuronal ceroid lipofuscinosis (LINCL) is a neurodegenerative disorder associated with mutations in the Cln2 gene encoding tripeptidyl-peptidase I (TPP1)." (PMID 29523085, 2018). "Late-infantile neuronal ceroid lipofuscinosis (LINCL) is a recessive genetic disease of childhood caused by deficiencies in the lysosomal protease tripeptidyl peptidase I (TPP1)." (PMID 22792360, 2012). "NCL2 (Jansky-Bielschowsky disease; MIM #204500) is one of the most frequent NCLs and is caused by autosomal recessive mutations in the TPP1 gene resulting in a deficiency of the lysosomal enzyme tripeptidyl peptidase 1 (TPP1)." (PMID 35425725, 2022). "Another subclass of NCL, late infantile NCL (LINCL), is caused primarily by mutations in tripeptidyl peptidase 1 (TPP1, also known as CLN2), a lysosomal peptidase." (PMID 34776869, 2021). "CLN2 disease previously referred to as late-infantile neuronal ceroid lipofuscinosis (LINCL) (OMIM # 204500) due to its usual presentation, is an autosomal recessive disorder, caused by pathogenic variants in the TPP1 gene on chromosome 11p15 (EC 3.4.14.9)." (PMID 33882967, 2021). "CNL2 also known as “Late Infantile Neuronal Ceroid Lipofuscinosis (LINCL),” derives from a defect in the lysosomal gene CLN2 encoding the enzyme tripeptidyl peptidase 1 (TPP1) (Kohlschütter and Schulz, 2016), resulting in the lysosomal accumulation of ceroid lipofuscin." (PMID 34690692, 2021).
epilepsy (20 papers, 2018 to 2025). A brain disorder characterized by episodes of abnormally increased neuronal discharge resulting in transient episodes of sensory or motor neurological dysfunction, or psychic dysfunction. "Epilepsy-associated genes (TPP1, BCKDK, ALG3, and PACS1) were upregulated and enriched in PZ and showed higher expression in the TLE as compared with the healthy control scRNA data." (PMID 39541170, 2025). "Considering the high prevalence of CLN2, this study supports the addition of TPP1 (CLN2) and other genes linked to NCLs in diagnostic NGS-based epilepsy panels." (PMID 34469436, 2021). "Whereas TPP1 is currently incorporated in the majority of comprehensive epilepsy gene panels, our study findings underscore the importance of including TPP1 on ataxia and developmental delay (which include language and motor components) gene panels as well." (PMID 33356800, 2021). "CLN2 disease is caused by deficiency of the lysosomal enzyme TPP1 and is characterized by rapid psychomotor decline and epilepsy." (PMID 34469436, 2021). "Currently, the potential diagnosis of CLN2 disease is initially based on clinical findings (i.e., retinopathy, motor abnormalities, dementia and/or epilepsy), followed by CLN2 gene sequencing and assessment of TPP1 enzymatic activity to confirm the diagnosis." (PMID 30323181, 2018). "The patient has reduced TPP1 enzyme activity and clinical phenotypes like epilepsy, regression of mental and motor milestone, choreoathetosis, cerebral atrophy, and cerebellar atrophy were in line with the diagnosis." (PMID 30541466, 2018).
Ataxia (17 papers, 2017 to 2025). Ataxia refers to impaired coordination of voluntary muscle movement. "We identified the pathogenic splicing variant c.509-1G > C in TPP1 (NM_000391.3) in a 4-year-old girl with myoclonic epilepsy, language delay, mild cognitive impairment, tremor, ataxia, and neuroimaging abnormalities." (PMID 32631363, 2020). "A juvenile onset, progressive and protracted form of cognitive decline with myoclonus, dystonia, bradykinesia and ataxia was reported in three siblings and associated with compound heterozygosity in CLN2/TPP1, leading to stop codon formation and an aminoacid substitution." (PMID 35359645, 2022). "A well-established mouse model to study cLINCL was generated and characterized bytargeting the mouse gene Tpp1 in the Lobel laboratory,resulting in loss of detectable TPP1 activity, progressive neurological phenotypesincluding ataxia, and increased motor deficiency." (PMID 31003587, 2019). "A naturally occurring TPP1-deficient Dachshund model recapitulates the key features of human CLN2 disease, including ataxia, tremor, progressive brain atrophy, loss of vision, and a reduced life span." (PMID 35509995, 2022). "CLN2 is a specific subtype of NCLs caused by TPP1 loss of function, resulting in seizures, vision loss, dementia, cerebellar ataxia, sleep disorders, progressive psychomotor decline, and death in the first decade of life." (PMID 36362641, 2022). "Other atypical cases with a demonstrated partial TPP1 enzyme deficiency show prominent ataxia, but absence of seizures, cognitive regression or visual findings." (PMID 33377563, 2021). "Subjects with pathogenic variants in TPP1 which allow for minimal residual TPP1 enzymatic activity may not demonstrate a classical presentation, presenting later in childhood or even adulthood with variable symptoms including epileptic seizures, cerebellar ataxia, dysarthria, or gait disturbance." (PMID 39762319, 2025). "These patients, with 5% residual TPP1 activity in fibroblasts, have later disease onset than cLINCL patients (0.4% residual TPP1 activity), develop ataxia and cerebellar atrophy but not blindness or seizures." (PMID 34749772, 2021).
CLN2 disease (13 papers, 2018 to 2026). "Genetic testing and enzyme activity assays are also available for NCL subtypes caused by loss of a specific lysosomal enzyme (e.g. TPP1 activity in CLN2 disease)." (PMID 34870700, 2021). "Recombinant tripeptidyl tripeptidase 1 (TPP1, cerliponase alfa) was approved for the treatment of Ceroid Lipofuscinosis 2 (CLN2) disease following ICV enzyme infusion in a lateral ventricle." (PMID 35745855, 2022). "So as to develop a treatment of the brain in CLN2 disease, the TPP1 proenzyme was infused in children with CLN2 disease into a lateral ventricle with a chronically implanted Ommaya reservoir every 2 weeks at a dose of 300 mg of enzyme in a volume of 10 mL over a 4 h period." (PMID 35745855, 2022).
retinal degeneration (11 papers, 2018 to 2025). Degeneration of the retina. "This contrasts with the canine TPP1 null variant, where retinal degeneration is described as a progressive loss of inner retinal function, affecting the rod system more profoundly than the cone system." (PMID 34272513, 2021). "Periodic intravitreal injections of a recombinant human TPP1 protein resulted in inhibition of retinal degeneration and preserved retinal function in a CLN2 canine model." (PMID 40706588, 2025). "This study reported the inhibition of the retinal degeneration in the canine model after a single intravitreal administration of autologous bone marrow-derived stem cells transduced with a TPP1 expression construct." (PMID 30541466, 2018). "ERT administration does not alter the progressive retinal degeneration, probably because of the spectrum of the eye’s immune privilege and blood-retina CNS barrier, but intravitreal administration of rhTPP1 has slowed retinal degeneration in four TPP1-null dogs." (PMID 34272513, 2021). "For instance, intraventricular injections of recombinant TPP1 or TPP1-encoding AAV vectors significantly delayed onset and progression of the brain pathology in a CLN2 canine model, but had no therapeutic impact on the progression of retinal degeneration and visual deterioration." (PMID 31578378, 2019).
Parkinson disease (7 papers, 2016 to 2025). A progressive degenerative disorder of the central nervous system characterized by loss of dopamine producing neurons in the substantia nigra and the presence of Lewy bodies in the substantia nigra and locus coeruleus. "Of those, five patients presented MDs such as dystonia or parkinsonism, spasticity, and suspicion of brain iron deposits or GP hypointensities; they were associated with variants in FBXO7, FUCA1, GLB1, TPP1, and KIF1A." (PMID 36233161, 2022). "Therefore, it is interestingthat the Tpp1-targeted neuroinflammation process correlates morestrongly with autoimmune types of neurodegenerative diseases (EAE and multiplesclerosis)than with AD or Parkinson’s disease." (PMID 31003587, 2019).
pulmonary fibrosis (6 papers, 2014 to 2025). Chronic progressive interstitial lung disorder characterized by the replacement of the lung tissue by connective tissue, leading to progressive dyspnea, respiratory failure, or right heart failure. "We showed that pulmonary fibrosis initiated by chronic stress in mouse models is mediated by the tumor suppressor protein FBW7-mediated degradation of TPP1." (PMID 35269498, 2022). "Similarly, degradation of TPP1 can aggravate stress-induced cell senescence and pulmonary fibrosis by promoting AEC2 telomere uncapping." (PMID 39346776, 2024). "Interestingly, TELODIN prevents pulmonary fibrosis by competitively inhibiting pressure-induced TPP1 to accelerate turnover and telomere shortening." (PMID 39346776, 2024). "However, another recent study proposed that FBXW7 promotes senescence and pulmonary fibrosis, a typical age-related disease, by targeting the telomere protein TPP1 for degradation and accelerating the uncapping of telomere." (PMID 36104351, 2022). "Thus, to the emerged molecular target of TPP1 accelerated turnover, TELODIN prevents chronic stress induced premature pulmonary ageing and fibrosis, highlighting an effective protection of TPP1 and thus telomere dysfunction as a novel approach for intervention into pulmonary fibrosis." (PMID 35269498, 2022). "Other studies have shown that radiation exposure, oxidative stress, or bleomycin can trigger the degradation of TPP1 in AEC2s, triggering telomere unblocking, stem cell failure, DDR, fiber gene expression and pulmonary fibrosis." (PMID 39346776, 2024). "A recent study showed that overexpression of telomere protection protein 1 (TPP1) lengthened telomeres, expanded the AT2 cells population and inhibited bleomycin‐induced pulmonary fibrosis and respiratory dysfunction." (PMID 35274784, 2022). "We demonstrated that radiation exposure, oxidative stress (such as H2O2) or bacterial product bleomycin each trigger telomere shelterin protein TPP1 degradation in AEC2 stem cells, provoking telomere uncapping, DDR, stem cell exhaustion, fibrogenic gene expressions, and pulmonary fibrosis." (PMID 35269498, 2022). "Moreover, overexpression of TPP1 enhances respiratory physiological function with increased AEC2 stem cell population with lengthened telomeres, and confers pulmonary resistance to stress-induced onset of pulmonary fibrosis." (PMID 35269498, 2022).
Blindness (5 papers, 2021 to 2025). Blindness is the condition of lacking visual perception defined as a profound reduction in visual perception. "AAV9-mediated TPP1 gene therapy restores enzyme expression and reduces pathological hallmarks, offering promise for treating CLN2-associated blindness." (PMID 40706588, 2025).
Cognitive impairment (5 papers, 2020 to 2025). Abnormal cognition is characterized by deficits in thinking, reasoning, or remembering. "Endo-lysosomal proteins (e.g., HEXB, TPP1, SIAE) increased early in abundance alongside neurodegeneration-related proteins, and were followed by increases in metabolic proteins such as ALDOA, MDH1, and GOT1 at the mild cognitive impairment (MCI) stage." (PMID 40329321, 2025).
colorectal cancer (5 papers, 2013 to 2024). A primary or metastatic malignant neoplasm that affects the colon or rectum. "A rare variant of TPP1 confers an increased risk of colorectal cancer through interrupting TPP1-TIN2 interaction." (PMID 35057823, 2022). "We have demonstrated for the first time, to our knowledge, that TPP1 overexpression is associated with radioresistance in colorectal cancer cells in this work." (PMID 24260532, 2013). "Previous studies found that higher expression of TPP1 was involved in telomere elongation and contributed to the increase in malignant potential in B cell leukemia and colorectal cancer." (PMID 38722833, 2024). "In one study, a close correlation between PPT1/CLN1 and TPP1/CLN2 expression was reported in the progression and metastasis associated with colorectal cancer." (PMID 32430003, 2020). "TPP1 was shown to modulate also telomere homeostasis and confer radioresistance to human colorectal cancer cells." (PMID 32735728, 2020). "In conclusion, this study reveals that elevated TPP1 levels protect telomere from DNA damage and confer radioresistance in human colorectal cancer cells." (PMID 24260532, 2013). "We think the correlation between TPP1 levels and telomere length in colorectal cancer samples is of great importance." (PMID 24260532, 2013). "To further clarify the functions of TPP1, we investigated the role of TPP1 overexpression on radiosensitivity and telomere homeostasis in human colorectal cancer cells in this study." (PMID 24260532, 2013). "In this study, we found that elevated TPP1 expression significantly correlated with radioresistance and longer telomere length in human colorectal cancer cell lines." (PMID 24260532, 2013). "In our following study, we will collect more fresh cancer tissue samples and verify the relationship between TPP1 and telomere length in colorectal cancer using fresh cancer tissues." (PMID 24260532, 2013). "In this study, we demonstrated that TPP1 expression was closely correlated with telomere length and radiosensitivity in colorectal cancer cells." (PMID 24260532, 2013). "Our study demonstrated that TPP1 may participate in telomere homeostasis and could protect telomere from radiation in human colorectal cancer cells." (PMID 24260532, 2013). "Firstly we examined TPP1 protein expression and telomere lengths in five colorectal cancer cells." (PMID 24260532, 2013). "We demonstrated that elevated expressions of TPP1 in human colorectal cancer cells could protect telomere from DNA damage and confer radioresistance." (PMID 24260532, 2013). "In summary, our study for the first time indicates that TPP1 may be a potential target in the radiotherapy of colorectal cancer." (PMID 24260532, 2013).
dyskeratosis congenita (5 papers, 2017 to 2023). Dyskeratosis congenita (DC) is a rare ectodermal dysplasia that often presents with the classic triad of nail dysplasia, skin pigmentary changes, and oral leukoplakia associated with a high risk of bone marrow failure (BMF) and cancer. "A dyskeratosis congenita mutation in TPP1 (K170∆) that specifically compromises telomerase recruitment to telomeres is a valuable tool to evaluate telomerase-dependent telomere length maintenance in mice." (PMID 34645668, 2022). "Heterozygous carriage of TPP1 variants are associated with dyskeratosis congenita, bone marrow failure, and IPF, while homozygous carriage of a POT1 variant has been implicated in CP." (PMID 35420632, 2022). "Aberrations in the TPP1-TERT heterodimer formation might lead to short telomeres and severe diseases like dyskeratosis congenita and Hoyeraal-Hreidarsson syndrome." (PMID 37935941, 2023).
hepatocellular carcinoma (5 papers, 2014 to 2024). A malignant tumor that arises from hepatocytes. "Tripeptidyl peptidase 1 (TPP1) encodes a lysosomal protease capable of cleaving substrate N-terminal tripeptides, it served as an independent predictor for overall survival of hepatocellular carcinoma." (PMID 38430429, 2024). "As to RFX5 (Regulatory Factor X), being able to bind DNA and lend promoter specificity, was identified as a transcriptional activator of the TPP1 gene in hepatocellular carcinoma." (PMID 29713243, 2018). "Previous study showed that gradual loss of TRF2 promoted a DNA damage response in U2OS cells, our previous study showed that DHA could downregulate telomere shelterin component TPP1 in hepatocellular carcinoma." (PMID 32351616, 2020). "Tripeptidyl-peptidase 1 (TPP1) is overexpressed in hepatocellular carcinoma (HCC) tissues and significantly correlated with poor prognosis." (PMID 37087456, 2023).
Anxiety (4 papers, 2017 to 2025). Intense feelings of nervousness, tension, or panic often arise in response to interpersonal stresses. "Long telomeres in male blood cells were associated with reduced anxiety, while a positive correlation was found between Tpp1 expression and stereotypical behavior in both male and female VPA rats." (PMID 40272729, 2025).
bone marrow failure (4 papers, 2016 to 2022). "Unlike POT1, mutated TIN2 and TPP1 have not been observed in tumors, but germline mutations of these genes have been reported in human genetic diseases leading to bone-marrow failure." (PMID 27486974, 2016).
gastric cancer (4 papers, 2015 to 2026). A primary or metastatic malignant neoplasm involving the stomach. "Furthermore, the findings highlighted the pivotal role of TPP1 in gastric cancer progression and its potential as a therapeutic target." (PMID 41930144, 2026). "Besides, TPP1 was also demonstrated to act as a biomarker for gastric cancer during its progression." (PMID 37215115, 2023). "TPP1 was overexpressed in gastric cancer compared to adjacent normal tissue and confirmed that TPP1 promoted cancer cell proliferation." (PMID 38722833, 2024). "The qRT-PCR experiments were designed to detect the expression levels of the top 5 ranking HAX1, RNF2, PIM3, TPP1 and CAV1 genes in addition to the seed proteins ABCB1, AKT1 and BCL2 in both the SGC7901 gastric cancer cell line and the Adriamycin resistant SGC7901/ADR cell line." (PMID 26039373, 2015).
Lysosomal disease (4 papers, 2020 to 2023). "In the cln2 lysosomal disease model, mutants with knockdown and knockout of the tpp1/cln2 gene, which encodes the lysosomal protein tripeptidyl peptidase I (TPP-I), a soluble lysosomal aminopeptidase, accumulate cellular autofluorescent material." (PMID 35493081, 2022). "The three patients here described, MD-137 (FUCA1), MD-020 (GLB1), and MD-153 (TPP1), suffered from lysosomal diseases." (PMID 36233161, 2022).
Alzheimer disease (3 papers, 2021 to 2026). A progressive, neurodegenerative disease characterized by loss of function and death of nerve cells in several areas of the brain leading to loss of cognitive function such as memory and language. "Furthermore, evidence of stage 1 (TREM2 independent) and stage 2 (TREM2 dependent) disease-associated microglia (DAM) transcriptional signatures as described for Alzheimer disease models, start to be evident as early as 3 months in Tpp1−/− brains." (PMID 34749772, 2021).
autosomal recessive spinocerebellar ataxia 7 (3 papers, 2016 to 2022). Spinocerebellar ataxia autosomal recessive 7, also called SCAR7, is a slowly progressive hereditary form of spinocerebellar ataxia.